LRG1 (leucine rich alpha-2-glycoprotein 1)
Diseases named in the same sentence as LRG1 in open-access papers (continued):
Sharing a sentence is not in itself a finding about the gene and the disease.
serous ovarian cancer (1 paper, 2010). "The level of serum LRG1 from 58 women with serous ovarian cancer and 56 healthy control women was quantified by ELISA." (PMID 20831812, 2010). "After adjusting for multiple comparisons, the most notable difference was between serous ovarian cancer and other benign ovarian mass (p = 0.0007), with LRG1 concentrations being significantly higher in the serous ovarian cancer patients." (PMID 20831812, 2010). "Ascites fluid from 29 women with serous ovarian cancer was also tested by ELISA for LRG1 protein and was found to be elevated relative to serum levels with a mean value of 142.28 ± 73.56 μg/ml." (PMID 20831812, 2010). "Western blotting was used to determine if LRG1 protein was present at higher levels in serous ovarian cancer tissues compared to normal ovaries." (PMID 20831812, 2010). "Though the mean concentration of serum LRG1 in serous ovarian cancer patients differed between samples in the two data sets, differences in serum preparation and storage may have affected the quantity of LRG1 detected." (PMID 20831812, 2010). "It is possible that this ~51 kD glycoform of LRG1 is secreted by the serous ovarian cancer cells, and may contribute to the elevated levels of LRG1 quantitated by ELISA in the sera of these patients." (PMID 20831812, 2010). "Interestingly, four of the five serous ovarian cancer cell lines, OVCA433, OVCAR3, A2780-S, and A2780-CP expressed predominantly the ~47 kD form of LRG1 and little to none of the ~51 kD protein band." (PMID 20831812, 2010).
severe acute respiratory syndrome (1 paper, 2022). A viral respiratory infection caused by the SARS coronavirus. "Higher levels of circulating LRG1 have also been detected in patients with chicken pox, measles, mumps, severe acute respiratory syndrome (SARS) and HIV infection." (PMID 35062948, 2022).
squamous cell carcinoma (1 paper, 2015). A carcinoma arising from squamous epithelial cells. "Since both CRP and LRG1 were found to be significant predictive markers of survival for squamous cell carcinoma patients undergoing radiotherapy, we determined whether combining the levels of the two proteins linearly could be of value." (PMID 26425690, 2015). "The level of IL-6 was available for eight of the squamous cell carcinoma patients during treatment and so its correlation with CRP, LRG1 and LBP was investigated during radiotherapy." (PMID 26425690, 2015).
Ssc (1 paper, 2022). "Although LRG1 was found to be associated with decreased pulmonary function and active inflammation, it did not prove to be a good biomarker for Ssc disease activity." (PMID 36277429, 2022). "Circulatory CK17, LRG1 and MZB1 concentrations were increased in Ssc patients." (PMID 36277429, 2022).
thyroid cancer (1 paper, 2025). "Three downregulated proteins (protein S [PROS1], clusterin [CLU], and leucine-rich α-2-glycoprotein 1 [LRG1]) were found to be significantly associated with poor overall survival in thyroid cancer using differential analysis and Kaplan–Meier survival analysis." (PMID 40797389, 2025). "Correlation between LRG1 protein expression and clinicopathological parameters of thyroid cancer patients." (PMID 40797389, 2025). "Additionally, poorly differentiated thyroid carcinoma and PTC tumor cells at stage IV (AJCC 8th) PTC typically expressed low to moderate levels of PROS1, CLU, and LRG1." (PMID 40797389, 2025).
uveitis (1 paper, 2020). An inflammatory process affecting a part of or the entire uvea. "During uveitis, lrg1 upregulation is observed at the level of inflamed vessels on cryosections, while wholemounts show more diffuse lrg1 expression towards central retina than in naïve retina." (PMID 32183784, 2020). "Other genes were already implicated in other inflammatory disease models but not in uveitis, such as Lrg1, Ackr1 and Timp1." (PMID 32183784, 2020). "Finally, some of those genes are known to be involved in retinal function but not during uveitis specifically, such as Clu, Lrg1 and Fgf2." (PMID 32183784, 2020).
vasculitis (1 paper, 2021). "Among the KD-related proteins, LRG1 and AGT are associated with vasculitis and CALs in KD patients." (PMID 34499692, 2021).
cancer (86 papers, 2008 to 2025). A tumor composed of atypical neoplastic, often pleomorphic cells that invade other tissues. "Elevated levels of LRG1 in the bloodstream are often associated with inflammatory diseases, cancer, and cardiovascular disorders, making LRG1 a potential biomarker for disease activity." (PMID 40278724, 2025). "Here, tumor cells and the local tumor microenvironment, such as infiltrating immune cells and cancer-associated fibroblasts are potential sources of LRG-1." (PMID 38413424, 2024). "Increased C4B and C8A levels were correlated with cancer-associated inflammation and CRC progression, while cancer-associated inflammation was linked to the acute-phase reactant leucine-rich alpha-2-glycoprotein 1 (LRG1) and ceruloplasmin." (PMID 38911905, 2024). "High circulating LRG1 levels have been reported in many cancers, where LRG1 has been proposed, or used, as a prognostic and diagnostic marker." (PMID 38745756, 2024). "Of all the conditions in which LRG1 has been implicated, the clinical evidence for a role in cancer has become the most overwhelmingly compelling." (PMID 35062948, 2022). "Experiments have shown that cancer-associated fibroblasts upregulate the inflammatory protein LRG1 as well as inducing the EMT to promote CRC cell invasion and migration through the IL-6-STAT3 axis." (PMID 36358769, 2022). "Given that LRG1 was implicated in cell migration and invasion of other cancer types, we first determined if it also affects these initial steps of metastasis of ESCC." (PMID 32047555, 2020). "Leucine-rich alpha-2-glycoprotein-1 (encoded by LRG1) has been shown to be involved in multiple cancer progression and angiogenesis." (PMID 29029535, 2017). "Current literatures show that LRG1 is closely associated with cancer metastasis and poor prognosis, largely due to its effects on promoting cell invasion, angiogenesis, and migration." (PMID 26517349, 2015). "In addition, the multi‐functional secretory glycoprotein LRG1, has recently emerged as a potential biomarker in cancer patients at high risk for disease progression and recurrence." (PMID 39441646, 2024). "Leucine-rich ɑ-2-glycoprotein 1 (LRG1) has been implicated in the pathogenesis of various cancer types, however its role in ESCC is unknown." (PMID 32047555, 2020). "Studies have demonstrated that overexpression of LRG1 is associated with several types of tumors, and could be regarded as a diagnostic marker of cancers." (PMID 29029535, 2017). "LRG1 was significantly associated with cancer recurrence and poor prognosis, mainly because it played an important role in promoting cancer cell proliferation, invasion and migration through epithelial-to-mesenchymal transition (EMT) and Transforming growth factor-β (TGF-β) signaling pathway." (PMID 29029535, 2017). "Furthermore, in CRC stroma, cancer-associated fibroblasts (CAFs) produce IL-6 which upregulates the expression of metastasis-associated markers such as Leucine Rich Alpha-2-Glycoprotein 1(LRG1) via the JAK2/STAT3 signaling." (PMID 38520006, 2024). "Leucine-rich α2 glycoprotein (LRG1) has been identified as a marker of granulocyte differentiation, is involved in neovascularization by altering TGFα signaling at endothelial cells, and has recently been found elevated in plasma associated with distinct cancers including pancreatic." (PMID 30214418, 2018). "This could suggest that more samples might be needed to uncover the correlation, or could suggest that A1BG and LRG1 could be released into the circulation at the tumor onset stage (very early stage) and thus is generally associated with systematic cancer status." (PMID 23284758, 2012). "In mouse models of retinal vascular disease and cancer, LRG1 inhibition reduces neovascularisation and vascular dysfunction, possibly by removing its vascular destabilizing effects." (PMID 40277918, 2025).
cancer (continued). "Accordingly, LRG1 has been shown to be induced in patients with age-related macular degeneration, diabetic retinopathy, diabetic kidney disease, cancer, and cerebrovascular disease." (PMID 40277918, 2025). "LRG1 is an adipokine that has been shown to promote angiogenesis and promote immunotherapy resistance in cancers." (PMID 40327401, 2025). "If evidence from other diseases translates to cancer, other cell sources of LRG1 are likely to impact the tumor microenvironment." (PMID 38745756, 2024). "Recent work on the role of LRG1 in cancer showed that in some cancer models Lrg1 expression was mostly restricted to the vascular endothelium, with no expression detected in the perivascular mural cell population or the cancer cells themselves." (PMID 38745756, 2024). "LRG1 induction in the tumor mass and systemically in cancer is most probably through IL-6 and STAT3, with contributions from other signaling pathways." (PMID 38745756, 2024). "A growing number of studies support an integral role for LRG1 in cancer, where it has been shown to control cell viability and apoptosis, and promote epithelial cells to undergo EMT, a crucial step in tumor progression and metastasis." (PMID 38745756, 2024). "The filtered blue module (203 genes) contained several genes associated with various typesof cancers and cell cycle regulation, including TTK, PLK1, LRG1, and CDK1." (PMID 39439565, 2024). "Under physiological conditions, LRG1 is secreted primarily by the liver and has been found to be upregulated in various diseases such as cancer, cardiovascular disease, and inflammatory conditions." (PMID 39595649, 2024). "Alternative mechanisms for LRG1-driven angiogenesis have been proposed including regulation through HIF-1α, which is associated with resistance to cancer chemotherapy and increased patient mortality." (PMID 38745756, 2024). "There is also accumulating evidence that LRG1 has important angiocrine and angiopathic functions in cancer, not only by promoting the development of destabilized and immature neo-vessels, but also by impairing already established co-opted vasculature." (PMID 38745756, 2024). "Considering the importance of exosomes as messenger carrier in tumor development and the exosomal protein LRG1 in diseases including cancer, we investigated the function of LRG1 in PCa progression." (PMID 36681849, 2023). "The crucial contribution of LRG1 to tumour growth has been further confirmed in vivo where ablation or overexpression of Lrg1 in cancer cells respectively delayed or promoted growth of xenograft tumours." (PMID 35062948, 2022). "LRG1 has been shown to mediate cancer progression by mediating angiogenesis, promoting epithelial-mesenchymal transition (EMT), and inhibiting apoptosis." (PMID 35955698, 2022). "Binding between LRG1 and extracellular Cyt c has been shown to reduce apoptosis of lymphocytes and cancer cells in vitro." (PMID 36346018, 2022). "LRG1 has been shown to promote angiogenesis and regulate tumorigenesis, and is a promising biomarker candidate for several other cancer types." (PMID 36969742, 2022). "The effects of LRG1 on the cancer vasculature are therefore most likely inevitable and supportive of tumour progression." (PMID 35062948, 2022). "Leucine-rich alpha-2-glycoprotein-1 (LRG1) is a serum glycoprotein and have been increasingly recognized as biomarkers for certain diseases including microbial infections and cancer." (PMID 36180909, 2022). "With the exception of few publications reporting a putative protective role in tumour progression, a consistent number of proteomic studies have identified LRG1 as a valuable biomarker for the diagnosis and clinical assessment of a variety of cancer types." (PMID 35062948, 2022). "In accordance, blocking CAFs-LRG1 cascade was able to attenuate migrative and invasive capabilities of cancer cells, and liver metastasis in mouse model." (PMID 34930899, 2021).
cancer (continued). "Among them, five targets (APOH, CD14, ICAM1, LRG1 and SERPINC1) were reported to be associated with other cancers or prognostic significance." (PMID 34199928, 2021). "Among these cytokines, only recombinant IL-6 was able to significantly induce LRG1 expression in cancer cells." (PMID 34930899, 2021). "Accumulating evidence suggests that LRG1 is involved in the growth and progression of a variety of cancer types as significantly elevated expression of LRG1 in serum and solid tumours has been found to be associated with a poor prognosis." (PMID 34458833, 2021). "The expression of LRG1 in many cancers and the presence of LRG1 at high concentrations in the tumour microenvironment makes it a promising target." (PMID 34458833, 2021). "Further experiments demonstrated that CAFs induced EMT and promoted tumor migration and invasion by upregulation of LRG1 in cancer cells through the IL-6-STAT3 axis." (PMID 34930899, 2021). "To test this, we performed LRG1 knockdown in cancer cells when cultured with CAF conditioned medium." (PMID 34930899, 2021). "Taken together, these data unequivocally confirmed that CAFs-secreted IL-6 induced LRG1 expression through downstream activation of JAK2/STAT3 signaling in cancer cells." (PMID 34930899, 2021). "As anticipated, silencing of LRG1 was able to dramatically impair CAFs-induced EMT accompanied by decreased phosphorylation of Smad1/5 in cancer cells." (PMID 34930899, 2021). "Human LRG1 was observed in the culture fluid of the parental carcinoma cells leading the investigators to propose that extracellular LRG1 was likely responsible for the TGF-β1-induced apoptosis of the parental cells." (PMID 34692699, 2021). "To analyze the expression of LRG1 in detail, we classified LRG1 expression in ccRCC patients stratified by patient sex, age, race, grades, or cancer stage." (PMID 32337221, 2020). "In this study, we detected TGF-β mRNA expression in the 786-O cancer cell line after LRG1 stimulation and found that TGF-β expression was obviously increased." (PMID 32337221, 2020). "Further studies are warranted to address such discrepancies and to explore the involvement of LRG1 in other cancer types." (PMID 32047555, 2020). "Western blotting also showed significantly higher LRG1 expression in the carcinoma tissue samples than in the paracarcinoma tissue samples." (PMID 32337221, 2020). "qPCR showed that LRG1 mRNA expression was significantly upregulated in the ccRCC carcinoma tissue samples." (PMID 32337221, 2020). "As shown by the result of TMA-based IHC, immunoreactivities of LRG1 were mainly present in the cytoplasm in most of the cancer cells and occasionally observed in adjacent normal colorectal tissues." (PMID 29029535, 2017). "As shown by the result of TMA-based IHC, immunoreactivities of LRG1 were mainly present in the cytoplasm in most of the cancer cells." (PMID 26517349, 2015). "This led us to explore the levels of serum LRG1 among women with different types of benign and malignant ovarian masses." (PMID 20831812, 2010). "All of these LRG1 levels were higher than those of the non-cancer healthy controls from the original set of sera tested." (PMID 20831812, 2010). "By immunocytochemistry, LRG1 was localized to the cytoplasm of all of the ovarian cell lines tested, both cancer and normal, and was observed on the plasma membrane of most." (PMID 20831812, 2010). "However, the expression, impact, and potential mechanisms of LRG1 on malignant carcinomas remain controversial." (PMID 40797389, 2025). "Meanwhile, overexpression of LRG1 could reverse the AGAP2-AS1-knockdown mediated effects in cancer cells." (PMID 39124865, 2024). "Increased LRG1 expression in the serum has been demonstrated in multiple cancer types." (PMID 38658967, 2024). "In addition, raised blood LRG1 levels have been established as a tumor biomarker with potential clinical value and also as a predictive marker for cancer onset." (PMID 38745756, 2024).
cancer (continued). "Consequently, an increasing number of studies have reported an aberrant activation and functional role of LRG-1 in cancer." (PMID 38413424, 2024). "Indeed, high LRG1 levels in cancer patients' plasma correlate with poor prognosis and survival, and resistance to standard of care therapy." (PMID 38745756, 2024). "LRG1 has previously been described to promote cancer pathogenesis, either directly or indirectly." (PMID 37089863, 2023). "LRG1 is a glycoprotein involved in inflammation, angiogenesis, and cancer progression, as well as in the regulation of ECM synthesis and remodeling, although the precise molecular mechanisms remain unknown." (PMID 37569820, 2023). "Interestingly, serum LRG1 and neutrophil-derived LRG1 have different glycosylation patterns, and aberrant glycosylation patterns on LRG1 have been observed in cancer patients." (PMID 37121976, 2023). "In addition, LRG1 has also been reported to affect other cell types (including epithelial, immune, mesenchymal and cancer cells) mostly by modulating the TGFβ signalling pathway in a context-dependent manner." (PMID 35062948, 2022). "Pathological levels of LRG1 on the other hand, frequently driven by ectopic overexpression of LRG1 at the sites of pathology as observed in some cancers, inflammatory conditions and eye disease, have strong biological activity which appears, at least in part, mediated by coercion of TGFβ signalling." (PMID 34987199, 2022). "Nonetheless, while further studies are needed to elucidate the full range of activities LRG1 exerts during tumour progression, the evidence here reported firmly paves the way for LRG1 to become a novel and multifunctional target for the treatment of various cancer types." (PMID 35062948, 2022). "Low LRG1 levels impair resolution of inflammation, and the resulting high level of proinflammatory activity may potentiate survival of disseminated cancer cells in the proximity of surgical margins." (PMID 36353660, 2022). "Aberrant neovascularization contributes to cancer, so LRG1 might be a potential target for regulating pathological angiogenesis." (PMID 35371990, 2022). "However, in many conditions, including viral infections, diabetes, autoimmune and cardiovascular disease, fibrosis, and cancer, LRG1 levels are elevated both locally and systemically." (PMID 35318338, 2022). "In this study, we attempt to evaluate whether LRG1 is a suitable target for an ADC based cancer therapy." (PMID 34458833, 2021). "Conversely, adding neutralizing antibody either targeting IL-6 or IL-6R could efficiently block the induction of LRG1 mediated by CAFs, supporting that IL-6 was the essential effector derived from CAFs to promote LRG1 expression in cancer cells." (PMID 34930899, 2021). "Additionally, through the analysis of proteomic mass spectrometry, there was a higher level of leucine-rich alpha-2-glycoprotein 1 (LRG1) expression in urinary exosomes detected in cancer patients." (PMID 33922480, 2021). "The silencing of LRG1 has been reported to inhibit cell apoptosis of different cancers 28, 29, yet our study showed that LRG1 may promote apoptosis of ESCC cells as a tumor suppressor." (PMID 32047555, 2020). "Other markers (Alpha-1-acid glycoprotein 2 (ORM2), Alpha-1B-glycoprotein (A1BG), Haptoglobin (HP), and Leucine-rich alpha-2-glycoprotein (LRG1), etc.)were found to create an ambiguous core involved in cancer development but also to exactly promote tumor progression in the early stages." (PMID 32023884, 2020). "The high expression of LRG1 was found to promote the invasion and migration of those cancer cells." (PMID 32047555, 2020). "While serum LRG1 levels might be used as an indicator for tumor diagnosis 11-13, the expression, impact and potential mechanisms of LRG1 on malignant carcinomas remains controversial." (PMID 32047555, 2020).